GLA (galactosidase alpha)
Diseases named in the same sentence as GLA in open-access papers (continued):
Sharing a sentence is not in itself a finding about the gene and the disease.
Fabry disease (continued). "Fabry disease is categorized as classic or late onset, according to the presence or absence of early classic manifestations—acroparesthesia, clustered angiokeratoma, cornea verticillata, hypoanhidrosis, etc.—and the type of GLA mutation." (PMID 29553830, 2018). "Mutations in the α-Gal A gene (GLA, Xq22) have been proven to be responsible for Fabry disease." (PMID 30587147, 2018). "In Fabry disease, to date more than 900 mutations in the GLA gene have been identified, but a percentage of these are classified by scientific community as genetic variants of unknown significance (GVUS)." (PMID 30477121, 2018). "In one patient we identified a novel variant in the GLA gene, associated with Fabry disease." (PMID 28797094, 2017). "Fabry’s disease (OMIM # 301500) is an X-linked sphingolipidose characterized by deficient activity of a lysosomal hydrolase encoded by the GLA gene, α-galactosidase A. The disease phenotype is a result of the intracellular and extracellular build-up of non-metabolized glycosphingolipids." (PMID 29186855, 2017). "This is the confusable case of HOCM with Fabry disease with the GLA E66Q mutation." (PMID 27160240, 2016). "Fabry disease (OMIM #301500) is caused by mutations in the gene encoding alpha-galactosidase A (GLA) on chromosome Xq22, which leads to the systemic accumulation of globotriaoslyceramide (Gb3) and related glycosphingolipids in body fluids and affected tissues, mainly brain, heart, and kidney." (PMID 25126087, 2014). "Fabry disease (FD) is an X-linked hereditary defect of glycosphingolipid storage caused by mutations in the gene encoding the lysosomal hydrolase α-galactosidase A (GLA, α-gal A)." (PMID 23935525, 2013). "Fabry disease is an X-chromosome linked disease including 431 different mutations for the GLA gene." (PMID 24223300, 2013). "This suggests that the antibody production in male patients with Fabry disease may be associated with the deficiency of GLA protein." (PMID 24236025, 2013). "Fabry disease is caused by mutations in the gene (GLA) that encodes α-galactosidase A (α-Gal A)." (PMID 21598360, 2011). "Fabry disease (FD) is a rare, progressive, and multisystem storage disorder caused by α-galactosidase A (GLA) gene variants leading to systemic globotriaosylceramide (Gb3) deposition." (PMID 40161167, 2025). "Fabry disease (FD) is a lysosomal storage disorder caused by pathogenic variants in the gene encoding alpha-galactosidase A (GLA)." (PMID 40648776, 2025). "Fabry disease (FD) is a multisystemic X-linked lysosomal storage disorder caused by mutations in the GLA gene, which encodes the enzyme α-galactosidase A (α-Gal A)." (PMID 39861752, 2025). "Fabry disease (FD) is a rare genetic disorder due to mutations in the galactosidase alpha (GLA) gene, leading to partial or complete loss of activity of the encoded α-galactosidase A (α-Gal A)." (PMID 40520931, 2025). "Fabry disease (FD) is an X-linked lysosomal storage disease, caused by mutations in the GLA gene on the X chromosome, resulting in a deficiency of the lysosomal enzyme α-GAL." (PMID 39937021, 2025). "Fabry disease (FD) is a lysosomal storage disorder resulting from disease-causing variants in the GLA gene." (PMID 39937009, 2025). "Fabry disease (FD) is an uncommon X-linked lysosomal storage disorder stemming from alterations in the GLA gene located at Xq22.1." (PMID 41272030, 2025). "Fabry disease (FD) is an X-linked lysosomal storage disease caused by a mutation of GLA, a gene for α-galactosidase A (α-GLA) enzyme." (PMID 40640933, 2025). "Fabry disease (FD) is a rare X-linked lysosomal storage disorder characterised by a deficiency in α-galactosidase A activity resulting from mutations in the GLA gene." (PMID 40981160, 2025). "Fabry disease (FD) is a monogenic deficiency disease caused by pathogenic-variants of the galactosidase-a (GLA) gene." (PMID 41171875, 2025).
Fabry disease (continued). "Fabry disease (FD) is a rare X-linked lysosomal storage disorder caused by mutations in the GLA gene, which encodes the enzyme α-galactosidase A (α-Gal A)." (PMID 39857728, 2025). "Fabry disease (FD) is a rare disorder caused by variants in the GLA gene encoding α-galactosidase A (GALA), leading to end-stage kidney disease (ESKD), among other health issues." (PMID 40583864, 2025). "Fabry disease (FD) is an X-linked recessive inheritance lysosomal storage disorder caused by pathogenic mutations in the GLA gene leading to a deficiency of the enzyme alpha-galactosidase A (α-Gal A)." (PMID 38474401, 2024). "Fabry disease (FD) is a rare, inherited genetic disorder caused by the deficient activity of alfa galactosidase A (GLA), which results in the excessive deposition of lipids in the tissue and is characterized by chronic low-grade systemic inflammation." (PMID 38995008, 2024). "A CRISPR/Cas9-mediated knockout of the GLA gene together with the overexpression of a number of different mutant variants allowed establishing a correlation between enzyme activity levels and ER retention and, thereby, furthered the understanding of the full clinical presentation of Fabry disease." (PMID 39449071, 2024). "Fabry Disease (FD) in an X-linked inherited lysosomal storage disorder due to pathogenic variants in the galactosidase-α (GLA) gene, resulting in deficiency of the enzyme α-galactosidase A (α-GAL A)." (PMID 38607539, 2024). "Fabry disease (FD) is a lysosomal storage disorder caused by pathogenic variants in the GLA gene with a very broad phenotypic spectrum." (PMID 39273698, 2024). "Fabry disease (FD) is a rare, hereditary, X-linked recessive lysosomal storage disorder caused by various mutations in the α-galactosidase A (GLA) gene." (PMID 39564058, 2024). "Fabry disease (FD) is a glycoshingolipid lysosomal storage disorder resulting from a deficiency in the α-galactosidase A (α-GalA) enzyme due to mutations in the GLA gene." (PMID 39056771, 2024). "Fabry disease (FD) is a progressive, X-linked lysosomal disorder caused by deficient or absent lysosomal α-galactosidase A (α-Gal A) activity due to variants in the GLA gene." (PMID 39636942, 2024). "Fabry disease (FD) is an X-linked sphingolipid lysosomal storage disorder caused by mutations in the GLA gene, which encodes for the enzyme α–galactosidase A (α–Gal A)." (PMID 39384640, 2024). "Fabry disease (FD) is a rare hereditary multi-system disease caused by variants of the GLA gene, leading to reduced α-galactosidase A activity and, as a result, to the accumulation of toxic glycosphingolipids in various organs and tissues." (PMID 38002959, 2023). "Fabry disease (FD) is an X-linked disorder of glycosphingolipids that is caused by mutations of the alpha galactosidase (GLA) gene that codes for alpha galactosidase A, leads to dysfunction of many cell types and includes a systemic vasculopathy." (PMID 37807078, 2023). "Fabry disease (FD) is an X-linked, hereditary dysfunction of glycosphingolipid storage caused by mutations in the GLA gene encoding alpha-galactosidase A enzyme." (PMID 37914990, 2023). "Fabry Disease (FD) is a rare lysosomal storage disorder caused by mutations in the GLA gene on the X chromosome, leading to a deficiency in α-galactosidase A (AGAL) enzyme activity." (PMID 38254927, 2023). "Fabry disease (FD) is a rare genetic condition caused by mutations in the GLA gene, located on the X chromosome in the RPL36-HNRNPH2 readthrough genomic region." (PMID 38155709, 2023). "Fabry disease (FD) is a recessive monogenic disease linked to chromosome X due to more than two hundred mutations in the alfa-galactosidase A (GLA) gene." (PMID 38203231, 2023). "Anderson-Fabry disease (FD) is an X-linked lysosomal storage disorder caused by mutations in the GLA gene, which results in an impairment of the hydrolase α-galactosidase A (aGAL)." (PMID 37014703, 2023).
Fabry disease (continued). "Fabry disease (FD) is an X-linked inherited disorder caused by the deficient activity of a lysosomal hydrolase, α-galactosidase A (GLA, EC 3.2.1.22)." (PMID 36624895, 2023). "Fabry Disease (FD) is a monogenic X-chromosome-linked lysosomal storage disorder caused by mutations in the GLA gene, which codes for the lysosomal enzyme α-galactosidase A (α-GAL)." (PMID 37259462, 2023). "Fabry disease (FD) is a rare, hereditary, X-linked pathology caused by various mutations in the GLA gene, responsible for encoding the α-galactosidase A (α-GLA) enzyme." (PMID 38133204, 2023). "Fabry disease (FD) is a multisystem lysosomal storage disorder induced by a mutation in the alpha-galactosidase A (GLA) gene located on the X chromosome." (PMID 35163813, 2022). "Fabry Disease (FD) is a rare X- linked storage disease caused by mutations in the a-galactosidase A (GLA) gene leading to reduced activity of the encoded lysosomal enzyme (α-Galactosidase Α, α-Gal)." (PMID 34751898, 2022). "Fabry disease (FD) is a rare X-linked disease due to a multiverse of disrupting mutations within the GLA gene encoding lysosomal α-galactosidase A (AGAL)." (PMID 36499585, 2022). "Fabry disease (FD) is a rare, monogenic X-chromosome-linked lysosomal storage disorder caused by mutations in the GLA gene." (PMID 36818911, 2022). "Fabry disease (FD) is a genetic disease, with X-chromosome linked inheritance, due to variants in the GLA gene that encodes the α-galactosidase A (α-GAL) enzyme." (PMID 35238862, 2022). "Fabry disease (FD) (OMIM 301500) is an x-inherited glycosphingolipid storage disorder due to mutations in α-galactosidase A (GLA) gene; the deficient enzyme activity determines a multi-organ disease with progressive manifestations." (PMID 34609660, 2022). "As such, further exploration of differences between cases and controls on the degree of hearing loss or tinnitus is not possible, as possible associations between the severity of auditory phenotypes and the severity of Fabry disease may be caused by different pathogenic GLA gene variants." (PMID 36556012, 2022). "Fabry disease (FD) is a rare X-linked hereditary, lysosomal storage disease caused by mutations in the GLA gene (located on the X chromosome)." (PMID 36415240, 2022). "Fabry disease (FD) is a relatively rare X-linked hereditary disease caused by mutations in the GLA gene that results in deficient α-galactosidase A (α-Gal A) enzyme activity." (PMID 36415240, 2022). "Fabry disease (FD), a rare X-linked multiorgan disorder, develops based on >900 known mutations in the alpha-galactosidase A (GLA) gene coding for the homonymous GLA enzyme, which is part of the cellular lipid metabolism." (PMID 35681422, 2022). "Fabry disease (FD) is a rare X-linked recessive lysosomal storage disease caused by mutations in the α-galactosidase A (GLA) gene, leading to a deficient activity of α-GLA." (PMID 35884826, 2022). "Fabry disease (FD) is a rare life-threatening disorder caused by deficiency of the alpha-galactosidase A (GLA) enzyme with a characteristic pain phenotype." (PMID 35681422, 2022). "Fabry disease (FD) is a progressive, multisystemic, X-linked inherited lysosomal storage disease caused by pathogenic mutations in the α-Galactosidase A (GLA) gene." (PMID 36064417, 2022). "Fabry disease (FD) is an X-linked lysosomal storage disorder caused by mutations in the galactosidase A (GLA) gene that result in deficient galactosidase A enzyme and subsequent accumulation of glycosphingolipids throughout the body." (PMID 34204530, 2021). "Fabry disease (FD) is a lysosomal storage disorder caused by deficient alpha-galactosidase A activity in the lysosome due to mutations in the GLA gene, resulting in gradual accumulation of globotriaosylceramide and other derivatives in different tissues." (PMID 33924567, 2021).
Fabry disease (continued). "Fabry disease (FD) is an X-linked lysosomal storage disorder caused by a deficiency in the α-galactosidase A (GLA) enzyme, leading to the accumulation of globotriaosylceramide (Gb3) in multiple organ tissues and blood vessels, with increased stroke risk." (PMID 33078310, 2021). "Fabry disease (FD) is a rare X-linked disorder of glycosphingolipid metabolism caused by pathogenic variants within the alpha-galactosidase A (GLA) gene, often leading to neurological manifestations including stroke." (PMID 34441839, 2021). "Fabry disease (FD) is a lysosomal storage disease caused by mutations in the gene for the α-galactosidase A (GLA) enzyme." (PMID 34204583, 2021). "Fabry disease is an X‐linked disease characterized by the accumulation of globotriaosylceramide (Gb3) and other glycosphingolipids in cellular lysosomes, caused by a deficient activity of the alpha‐galactosidase A (GLA) enzyme, secondary to pathogenic genetic variants of the GLA gene." (PMID 33738082, 2021). "Fabry disease (FD) is a multisystem X-linked lysosomal storage disorder caused by a mutation in the alpha-galactosidase A (GLA) gene." (PMID 34300196, 2021). "Fabry disease (OMIM-301500, FD) is a lysosomal storage disease with X-linked inheritance secondary to mutations in the GLA gene, which cause absence or decreased activity of the lysosomal hydrolase a-galactosidase A (a-gal A)." (PMID 33924567, 2021). "Fabry disease (FD) is a rare X-linked disease caused by mutations in GLA gene with consequent lysosomal accumulation of globotriaosylceramide (Gb3)." (PMID 33531072, 2021). "Fabry disease is a rare X-linked inherited disorder caused by deficiency of α-Galactosidase A. Hundreds of mutations and non-coding haplotypes in the GLA gene have been described; however, many are variants of unknown significance, prompting doubts about the diagnosis and treatment." (PMID 31996269, 2020). "Fabry disease (FD) is a rare inherited glycosphingolipid storage disorder caused by deleterious mutations in the GLA gene coding for the lysosomal enzyme α-galactosidase A (α-GalA)." (PMID 33109218, 2020). "Anderson-Fabry disease (FD) is a X-linked lysosomal disorder, due to deficiency of the enzyme α-galactosidase caused by mutations in the GLA gene (located on the long arm of the X chromosome at Xq22)." (PMID 32264911, 2020). "Fabry disease (FD) is a X-linked inherited disorder caused by mutations in the GLA gene, which results in the deficiency of α-galactosidase A (α-Gal A)." (PMID 32843101, 2020). "Fabry Disease (FD) (OMIM 301500) is an X-linked disorder arising from a defect in GLA, causing dysfunction with α-galactosidase A and the storage of Gb3." (PMID 32260582, 2020). "Fabry disease (FD) is caused by mutations in the GLA gene that encodes lysosomal α-galactosidase-A (α-gal-A)." (PMID 31491876, 2019). "Fabry disease (FD) is a sphingolipidosis caused by a mutated alpha-galactosidase A, encoded by the GLA gene." (PMID 31771289, 2019). "Fabry disease (FD) is a rare X-linked recessive hereditary systemic disorder with nearly complete penetrance in male patients with mutations in the GLA gene." (PMID 30853972, 2019). "Fabry disease (FD) is an X-linked disorder, where mutations in the GLA gene result in a deficiency of the enzyme α-galactosidase A (α–Gal A) (EC entry 3.2.1.22)." (PMID 30633777, 2019). "Patientswith HCM may have GLA mutations and Fabry disease should be ruledout." (PMID 31291414, 2019). "Fabry disease (FD) is a X-linked lysosomal storage disorder characterized by mutations in the GLA gene on the X chromosome encoding the lysosomal enzyme, α-galactosidase A (α-Gal A)." (PMID 31555645, 2019). "Fabry disease (OMIM 301500; FD) is an X-linked metabolic disorder caused by mutations in the GLA gene, of which over 900 mutations (HGMD® July 2017) have been reported." (PMID 29621274, 2018).
Fabry disease (continued). "Fabry disease (FD) is an X-linked recessive multi-systemic storage disorder caused by a decreased activity of the lysosomal enzyme alpha-Galactosidase A (GLA)." (PMID 30159316, 2018). "Fabry Disease (FD) is a rare x-linked disorder characterized by an abnormal function of the lysosomal enzyme alpha-galactosidase A (GLA), involved in the cleavage of galactose residuals of globotriaosylceramide-3 (Gb3)." (PMID 28672034, 2017). "Fabry disease (FD) is a rare X-linked recessive genetic disorder caused by a deficient activity of the lysosomal enzyme alpha-galactosidase A (GLA) and is characterised by intra-lysosomal accumulation of globotriaosylceramide (Gb3)." (PMID 28933415, 2016). "Anderson-Fabry disease (FD) is a rare, X-chromosomal inherited lysosomal storage disorder resulting from currently over 800 known pathogenic alpha-galactosidase A gene (GLA) mutations." (PMID 27431810, 2016). "Fabry disease (FD) is a rare X-linked disease caused by enzyme α-Galactosidase A (Gal A)deficiency as a result of GLA gene mutations." (PMID 26269958, 2015). "Fabry disease (FD) results from mutations in the gene (GLA) that encodes the lysosomal enzyme α-galactosidase A (α-Gal A), and involves pathological accumulation of globotriaosylceramide (GL-3) and globotriaosylsphingosine (lyso-Gb3)." (PMID 23472096, 2013). "However, ERT often leads to the development of circulating immunoglobulin G (IgG) against rhGLA among male patients with Fabry disease, who completely lack the GLA protein, and these antibodies may cause allergic reactions and/or reduce the efficacy of ERT." (PMID 24236025, 2013). "Anderson-Fabry disease (FD) is an X-linked lysosomal storage disorder caused by pathogenic variants in the GLA gene, resulting in deficient α-galactosidase A activity and progressive accumulation of globotriaosylceramide (Gb3) and its derivative lyso-Gb3 within lysosomes." (PMID 41827876, 2026). "Fabry disease (FD) is an X-linked lysosomal storage disorder caused by mutations in the GLA gene, which encodes for Alpha Galactosidase-A (α-Gal A)." (PMID 42037485, 2026). "Fabry disease (FD; OMIM #301500) is a rare multisystemic X-linked lysosomal storage disorder caused by mutations in the α-galactosidase A (GLA) gene, which encodes the enzyme α-galactosidase A (α-Gal A), leading to its deficiency." (PMID 41310783, 2025). "In Fabry disease (OMIM #301500), the mutated gene, alpha-galactosidase A (GLA), is also found on the X chromosome (Xq21.3-q22)." (PMID 41150803, 2025). "Fabry disease (FD) is a rare X-linked lysosomal storage disorder caused by variants in the α-galactosidase A (GLA/AGAL) gene leading to impaired breakdown of glycosphingolipids and systemic accumulation of globotriaosylceramide (Gb3), particularly in vessels of affected organs." (PMID 41402951, 2025). "In this theme, a study showed that abnormal methylation of the GLA gene can disrupt autophagy in Fabry disease." (PMID 41150803, 2025). "Patients with clinical suspicion of Fabry disease undergo a diagnostic workup that includes an evaluation of α-GALA enzyme activity, genetic analysis of the GLA gene, and the measurement of blood Lyso-Gb3, a soluble derivative of Gb3." (PMID 39859188, 2025). "Fabry disease (FD) is an X-linked, multisystemic, progressive lysosomal disorder caused by GLA variants resulting in alpha-galactosidase A deficiency." (PMID 40722192, 2025). "We applied the strategy to the diagnosis of Fabry disease or Hereditary Transthyretin Amyloidosis (GLA or TTR genes respectively)." (PMID 40495216, 2025). "Researchers created GLA-knockout (KO) human iPSCs and used these to develop kidney organoids that recapitulated Fabry disease phenotypes." (PMID 39931243, 2025). "Fabry disease (FD, OMIM #301500) is an X‐linked lysosomal disorder resulting from pathogenic variants in the GLA gene, which encodes the enzyme α‐galactosidase A (α‐Gal A)." (PMID 41246852, 2025).